FOXP3 (forkhead box P3)
Diseases named in the same sentence as FOXP3 in open-access papers (continued):
Sharing a sentence is not in itself a finding about the gene and the disease.
cancer (continued). "Polymorphisms in the FOXP3 gene may change its product quantitatively or functionally, thereby contributing to an immune imbalance in cancer." (PMID 28713192, 2017). "Furthermore, FOXP3 polymorphisms have also been associated with different types of cancer, such as Wilm's tumor, hepatocellular carcinoma, colorectal cancer, and nonsmall cell lung carcinoma." (PMID 28713192, 2017). "Additionally, regarding ICOS+ FOXP3+ Tregs, an increased prevalence in carcinoma was not only associated with the absolute number but also with the percentage of FOXP3+ cells." (PMID 27725696, 2016). "So far the results are stilling conflicting, whether the prognostic effect of FoxP3+ Tregs attributable to the biologic properties of specific cancer type, and whether the associations depend on differences in study methodologies was not known." (PMID 26462617, 2015). "Polymorphisms of the FOXP3 gene may change FOXP3 quantitatively or functionally, thereby contributing to an immune imbalance in cancer." (PMID 23759077, 2013). "However, its expression was also associated with infiltration of Treg in a cancer model suggesting that it could regulate Treg function through Foxp3 induction." (PMID 39934117, 2025). "Foxp3 TIL expression levels may also be associated with prognosis in cancer patients." (PMID 35326661, 2022). "Thus, it remains unclear whether allelic variants of the Foxp3 gene can affect immune surveillance of cancer." (PMID 31729760, 2020). "In addition, due to the strong association of FOXP3/miR‐198 levels with cancer status, they may have the potential as new biomarkers for clinical diagnose and prognosis." (PMID 30378283, 2018). "Likewise, monensin-mediated inhibition of Foxp3 iTreg development could, in part, explain the mechanisms underlying its effective re-purposing in the treatment of several different types of cancers." (PMID 28492364, 2017). "Therefore, developing approaches to prevent CD4+CD25+FOXP3+ Treg elevation with age may enhance T-cell-mediated immune response and further reduce the risk of cancer." (PMID 28253320, 2017). "However, the 25.38% overlap (associated genes) indicated that cancer cell-derived Foxp3 could also directly regulate gene transcription in TSCC cells." (PMID 25779374, 2015). "However, on the other hand, several works have demonstrated that the expression of FOXP3, especially in breast cancer cells, is an X-linked cancer suppressor gene and an important regulator of the epidermal growth factor receptor (HER2/ErbB2) and SKP2 oncogenes." (PMID 24350059, 2013). "Separately, in pancreatic cancer, losartan has been shown to reduce immunosuppressive genes and FOXP3+ cancer cells, underscoring its capacity to reverse key mechanisms of therapy resistance." (PMID 41486497, 2026). "The effective scores of CD8+ T cells, PD-1+CD8+ T cells, FOXP3+CD4+ T cells and FAP+ cells, which represents cancer-associated fibroblasts (CAFs), were higher in the DCB than those in the NDB." (PMID 40082418, 2025). "qRT-PCR analysis of these Tregs revealed that BST2 knockdown in the cancer cells led to a significant downregulation of the key Treg functional markers Foxp3 and IL-10." (PMID 41281378, 2025). "The mRNA expression of Foxp3 was increased by twofold in the cancer tissues treated with IMWA alone but completely reverted to their normal state with the additional application of AZD5582." (PMID 39917292, 2025). "Tregs, commonly known as CD4+CD25+Foxp3+, make up approximately 5% of the T‐cell population and diminish antitumor immunity by allowing cancer cells to evade the antitumor response." (PMID 40105652, 2025). "CD4+FOXP3+ Treg cells maintain self tolerance, suppress the immune response to cancer, and protect against tissue injury during acute inflammation." (PMID 40100289, 2025). "Elevated levels of FoxP3+ Tregs within the TME showed a positive correlation with poor prognosis in patients with various cancers." (PMID 39773913, 2025).
cancer (continued). "In the escape phase, cancer cells select immunosuppressive cells, including myeloid-derived suppressor cells (MDSCs), regulatory CD4+FOXP3+ T cells (Treg cells), and cancer-associated macrophages." (PMID 41155765, 2025). "The common markers of effector T cells, helper T cells, and regulatory T cells, which were CD8, CD4, and Foxp3, respectively, were stained on the cancer tissue sections of C57BL/6 mice." (PMID 39917292, 2025). "The literature indicates that the activation of T-reg cells can increase the risk of cancers such as HCC, with CD4+CD25+FoxP3+ T cells playing a significant role in this risk." (PMID 40881323, 2025). "FOXP3 is said to accelerate cancer development through a number of mechanisms including increasing the rate of lymphangiogenesis." (PMID 40365511, 2025). "In this research, we focused on characterizing the effects of GDF11 on the expression of FOXP3 and its implication in cancer cell aggressiveness." (PMID 40746879, 2025). "A strong positive correlation was observed between FOXP3 and PD-L1 expression (r=0.76), consistent with previous findings in other cancer types." (PMID 39857011, 2025). "The ratio of Foxp3-positive immune-suppressive regulatory T cells was increased in the TME of cancer tissues treated with IMWA alone but was decreased by the additional application of AZD5582." (PMID 39917292, 2025). "On the one hand, Treg cells, identified by expression of Foxp3, play critical roles in regulating immune responses and promoting immune tolerance in cancer." (PMID 40297156, 2025). "Numerous researches have investigated the correlation between SNPs in the Foxp3 gene and the development of various cancers." (PMID 39935826, 2025). "Together, our findings shed new light on the cellular and molecular functions of Foxp3 and provide a rationale for direct therapeutic targeting of Foxp3 in cancer." (PMID 40478934, 2025). "An increased frequency of circulating CD4+CD25+FOXP3 (forkhead box P3)+ Tregs is commonly observed in cancer patients." (PMID 40443670, 2025). "This work presents an alternative approach to implementing pre-clinical studies that advance and consider the lessons learned from GDF11 as a negative regulator of FOXP3 in this type of cancer." (PMID 40746879, 2025). "The expression of these molecules stabilizes FOXP3 and augments the suppressive capacity of Tregs, contributing to therapy resistance and immune escape across multiple cancers." (PMID 41394821, 2025). "Numerous researches have investigated the correlation between single nucleotide polymorphisms (SNPs) in the transcription factor forkhead box protein 3 (Foxp3) gene and the development of various cancers." (PMID 39935826, 2025). "A comprehensive meta-analysis found that the prognostic impact of FOXP3+ Tregs varies significantly across cancer types." (PMID 40806346, 2025). "Biomarkers linked to DSS were found in eight cancer types, with CALR, FOXP3, and NT5E identified in at least three cancers." (PMID 41150760, 2025). "The conditioned medium from cancer organoid #2 significantly increased the CD3+/CD4+/FOXP3+ Treg subset compared to that of the control, while knocking out galectin‐9 suppressed this subset." (PMID 38528665, 2024). "Using flow cytometry, we confirmed that ASO FOXP3 treatment resulted in decreased numbers of all cancer Tregs including intratumoral Tregs, analyzed separately." (PMID 39234236, 2024). "This article mainly summarizes the research progress on the expression mechanism and function of Foxp3+Treg and Foxp3 related features and functions in digestive system malignant tumors, which have been publicly published in publications such as Pubmed." (PMID 38919615, 2024). "In particular, FoxP3 expression was more strongly stained in cancer tissues than in the surrounding tissues." (PMID 39150932, 2024). "In many reports, FoxP3 staining in cancer tissue is often interpreted as infiltration of Treg cells." (PMID 39150932, 2024).
cancer (continued). "Foxp3 suppression or binding to miR-133a-3p can limit Foxp3 expression, which stimulates GC cell proliferation and autophagy, helping to deplete and remove damaged cells and maintain cancer cell homeostasis." (PMID 38919615, 2024). "The percentage for FoxP3 positive area in the cancer tissues (CC2) in the CC group was significantly higher than that in the Control group." (PMID 39150932, 2024). "According to the expression results of genes that suppress the proliferation of cancer cells and drive them to apoptosis, statistically significant differences were detected in FOXP3 and CASP3 gene expressions." (PMID 39770446, 2024). "Studying the regulatory mechanisms of Foxp3+ Treg cells and Foxp3 involvement in malignant tumors is of great significance for understanding and developing treatments for each disease." (PMID 38919615, 2024). "Tregs, a subset of CD4+ T cells, are closely related to the pathogenesis of cancer and express the transcription factor FoxP3." (PMID 39605905, 2024). "The skewing of elevated FOXP3Δ3 to FOXP3 ratios in cancer cells likely presents a survival advantage to the cancer cell." (PMID 39099201, 2024). "At mRNA level, cancer samples were much more sensitive with their FOXP3 mRNA downregulation than healthy donors PBMC samples, independently of the candidate ASOs used." (PMID 39234236, 2024). "CD3 is expressed on almost all T cells, CD8 is expressed on cytotoxic T cells, which can potentially kill cancer cells, and FOXP3 is expressed on regulatory T cells, which downregulateS immune response." (PMID 38704243, 2024). "It emphasizes the advancement of research on the regulatory mechanisms of Foxp3 in different malignant tumors of the digestive system, providing new insights for the exploration of anticancer treatments." (PMID 38919615, 2024). "In examining the role of FOXP3 in tumors cells, we described a gene expression program that promotes cancer cells through upregulation of PD-L1 expression and other inflammation-related genes and genes involved in EMT." (PMID 39099201, 2024). "Forkhead box P3 (FOXP3) is a transcription factor synonymous in T regulatory cell function but with increasingly described functions in cancer cells." (PMID 39099201, 2024). "We determined the position and identity of cells using mIF and identified B cells, T cells (CD8+ T cells, FoxP3+ T cells, and T-helper cells), macrophages, and cancer cells." (PMID 38514623, 2024). "The stabilization of CTLA4 expression by Foxp3, in turn, amplifies the attenuation of T-cell response in the context of cancer." (PMID 38617537, 2024). "Recently, AstraZeneca and Ionis Pharmaceuticals have used an older generation of ASO technology to target FOXP3 for cancer models and shown limited efficacy in their preclinical studies." (PMID 39234236, 2024). "Historically a key transcription factor driving T regulatory cell function, FOXP3 has an increasingly recognized role in cancer cells." (PMID 39099201, 2024). "MiR-125b and miR-133a-3p are overexpressed, thereby reducing the expression of FOXP3 and further inducing autophagy in cancer." (PMID 38572308, 2024). "High FoxP3 expression in cancer cells in the CC group and low expression in the CC+GL group, where cancer formation was suppressed by GL, suggest that FoxP3 expression in cancer cells is involved in the malignant transformation of cancer." (PMID 39150932, 2024). "Recent studies have revealed FOXP3 expression in various cancers, including gastric, pancreatic, liver, and breast cancer." (PMID 38331927, 2024). "COMP expression in the cancer cells was also associated with less infiltrating CD138+ B-cells (p = 0.038) and activated FoxP3+ T-cells (p < 0.001)." (PMID 38563861, 2024). "The T cell markers CD28 and FLT3LG expression decreased in cancer while FOXP3, IDO1, and ULBP2 expression increased." (PMID 39672307, 2024).
cancer (continued). "Our study suggests that C + D therapy promotes the infiltration of CD4+ and CD8+ CTLs and elevates the ratio of CD8+ T cells to FOXP3+ Tregs, eliciting local anti-cancer immunity in TME and resulting in prolonged survival outcomes." (PMID 39090653, 2024). "The modulatory effect of STAT3 on FoxP3 expression has been reported on Tregs infiltration in cancer." (PMID 39150932, 2024). "The immunosuppressive character of the TME is regulated by FOXP3, which promotes Treg pro-cancer function." (PMID 39272802, 2024). "Compared to normal tissues, FOXP3 is highly expressed in various cancers, including gastric cancer, esophageal cancer and breast cancer." (PMID 38674427, 2024). "While FAS is expressed in Tregs from healthy individuals and cancer patients, elevated FAS-L is seen only in Tregs from cancer patients, linked to poor CD8+ T-cell infiltration and FOXP3+ Treg predominance." (PMID 38891056, 2024). "Further independent studies in larger groups of patients of various ethnicities are needed to replicate and validate the present genetic and epigenetic associations of FOXP3 rs3761548 genotypes and FOXP3 methylation status to PTC risk and other cancer types." (PMID 39000267, 2024). "It is also necessary to develop panels containing MDSCs markers as well as other markers like CD19 (B cells), Granzyme B (activated T cells), Foxp3 (regulatory T cells), α-SMA (cancer associated fibroblasts, CAFs) and FAP (CAFs) to characterize the TME." (PMID 38877529, 2024). "Foxp3 was predominantly expressed in brownish-yellow granules in the nuclei of Tregs, distributed throughout the cancer tissue in CRC patients." (PMID 39104717, 2024). "Primary or secondary (i.e., acquired) resistance is a common occurrence in cancer patients and is often associated with high numbers of T regulatory (Treg) cells (CD4+CD25+FOXP3+)." (PMID 38318526, 2024). "Downregulation of FOXP3 in cancer Tregs was accompanied by significantly decreased mRNA expression of five out of nine tested exhaustion markers: CTLA-4, Tim-3, PD-1, LAG-3 and TIGIT in the endogenous T cells." (PMID 39234236, 2024). "FOXP3 was originally thought to be a Tregs-specific molecule, but recent studies have pinpointed that FOXP3 is expressed in a diversity of benign tumors and carcinomas." (PMID 38674427, 2024). "The prognostic value of CD4+FOXP3+ T cells has been confirmed in many cancers, but contradictory results have also been found in some cancers." (PMID 37868998, 2023). "Lastly, both USP7 and USP22 are involved in immunosuppression through stabilizing immune check-point inhibitor PD-L1 in cancer and FOXP3 in Tregs, and the significance of this feedback deserves to further study using immune-component cancer model." (PMID 37946202, 2023). "In our study, we identified the expression of GZMB, CD56, and the regulatory T cell (Tregs) marker FOXP3 within ‘immune-rich cancer cell islet’ regions." (PMID 37046826, 2023). "As FOXP3 isoforms lacking exon 2 or exon 7 are more likely to be trapped in nuclei, the relationship between Treg FOXP3 isoforms and cancer prognosis needs further research." (PMID 37868998, 2023). "Foxp3, a winged helix/forkhead family transcription factor, is a major regulator of Treg cell development and function, inducing various cancer cells." (PMID 37342563, 2023). "Nowadays, it is known that FOXP3 expression occurs not only in hematopoietic cells but also in cancer cells." (PMID 36672296, 2023). "Recent studies also demonstrate that USP22 plays a critical role in cancer immunosuppression through stabilizing FOXP3 activity in Treg and programmed death-ligand 1 (PD-L1) in cancer." (PMID 37946202, 2023). "New FoxP3 inhibitors augmented antitumor immunity and provided a therapeutic benefit in cancer models." (PMID 36980787, 2023). "IL-2 administration has been shown to increase CD4+CD25+Foxp3+ Treg numbers in patients with cancer." (PMID 38004268, 2023).
cancer (continued). "Cancer cells recruited the CD4_T_cells_c2_CXCL13, CD8_T_cells_c1_GZMK, CD8_T_cells_c4_IFIT3, NK_cells_KLRD1, and Treg_cells_FOXP3 clusters through the CXCL10‐CXCR3 ligand–receptor pair." (PMID 36529697, 2023). "Another limitation is our lack of a deep dive into the specific mechanisms driving differential FoxP3+Tregs expression between the cancer types." (PMID 38115302, 2023). "Regulatory T-cells (Tregs) play a vital role in disturbing immune environments in cancer patients and are widely defined as FoxP3 + CD4 + T-cells." (PMID 37884996, 2023). "We used mIHC to visually analyze GCPM cells at 15 h after treatment with PBS or CF33-hNIS-antiPDL1 for anti-PD-L1 scFv (green), EpCAM (brown for cancer cells), PD-L1 (purple), and Treg cells (yellow for FoxP3) expression." (PMID 37762490, 2023). "In fact, CCL5 promotes Treg infiltration, and cancer-FoxP3 (C-FoxP3) expressed on these T-regs promotes PD-L1 expression, which rationalizes targeting CCL5 in combination with PD-L1 inhibitors." (PMID 37488598, 2023). "The immune function of FoxP3 in Treg cells is clear, but the immune function of FoxP3 in cancer is unclear, especially in RCC progression." (PMID 37569676, 2023). "The transcription level of FoxP3 was compared with adjacent normal tissues from cancer patients, including ccRCC." (PMID 37569676, 2023). "On the other hand, Foxp3 expression in Jurkat cells is originally higher than that in other cancer cells." (PMID 38024862, 2023). "Immunofluorescence histochemical staining revealed infiltration of cancer cells by adiponectin‐expressing FOXP3 positive cells." (PMID 37674354, 2023). "In 726 IBCs, CD8+, FOXP3+, IL17+, PDL1+, PD1+ T-cell infiltration (TILs) were investigated in RECQL deficient and proficient cancers." (PMID 38134458, 2023). "To explore and confirm the transcription level of FoxP3 in ccRCC, we analyzed the FoxP3 mRNA level in 23 different cancer types." (PMID 37569676, 2023). "According to published reports, there is still controversy regarding the biofunction of FoxP3 in different types of cancer." (PMID 37569676, 2023). "EGFR was found to be expressed by Treg cells, and the AREG-EGFR signaling axis is critical for maintaining Foxp3 stability in Treg cells in patients with cancer." (PMID 37611111, 2023). "Recent studies have suggested that RUNX1 and Foxp3 can synergistically inhibit cancer cell proliferation and apoptosis, suppressing the growth and spread of cancer cells by inhibiting metabolic pathways and Ras or other signaling pathways." (PMID 37342563, 2023). "In EC, the accumulation of CD4+CD25+‐ and Foxp3+‐Tregs was supposed to be connect with cancer cell proliferation and poor clinical prognosis." (PMID 36226375, 2023). "Among carcinomas, a high number of Foxp3+ cells was significantly correlated with more aggressive histotype and grading and with the presence of lymphatic invasion, which is in agreement with previous studies." (PMID 36766393, 2023). "A significantly higher number of Foxp3+ cells were detected in grade III carcinomas compared to grade II carcinomas, as well as in tumors with lymphatic invasion and loss of ER-expression." (PMID 36766393, 2023). "CTLA-4 expressed on Treg cells can induce cancer regulatory effects via interaction with forkhead box P3 (FOXP3)." (PMID 36423060, 2022). "Tregs (CD4+ CD25+ Foxp3+) suppress immune responses to infectious pathogens, cancer, allogeneic organs, and stem cell transplantation." (PMID 35742877, 2022). "Large populations of FOXP3+ Tregs have been recognized in the TME, and their accumulation has been linked to poor prognosis in cancer." (PMID 36405735, 2022). "Negative associations were found between the frequencies of CD4+CD25+Foxp3+ and CD4+CD25+Foxp3+CD127low/− Treg cells and cancer stage (P = 0.015 and P = 0.059)." (PMID 36376825, 2022).